RNU6-1035P (RNA, U6 small nuclear 1035, pseudogene)
Gene: Small nuclear RNA gene on chromosome 9 (81,725,243 to 81,725,349, reverse strand). Ensembl gene ENSG00000207206.
Homologues: Orthologues: chimpanzee U6 (98% identical), macaque U6 (93% identical). Paralogues in human: RNU6-16P (89% identical), RNU6-25P (89% identical), RNU6-73P (89% identical), RNU6-820P (89% identical), RNU6-1 (88% identical), RNU6-1029P (88% identical), RNU6-15P (88% identical), RNU6-2 (88% identical), RNU6-20P (88% identical), RNU6-35P (88% identical), RNU6-393P (88% identical), RNU6-3P (88% identical), and 1288 more.